BRCA1 (BRCA1 DNA repair associated)
Diseases named in the same sentence as BRCA1 in open-access papers (continued):
Sharing a sentence is not in itself a finding about the gene and the disease.
triple-negative breast carcinoma (continued). "We previously analyzed genome-wide DNA methylation patterns in the context of BRCA1-mutated vs hypermethylated triple negative breast cancer (TNBC)." (PMID 36084090, 2022). "This case-control study examines the potential association between white blood cell BRCA1 promoter methylation and subsequent risk of incident triple-negative breast cancer and high-grade serous ovarian cancer." (PMID 36074460, 2022). "For patients with triple-negative breast cancer with germline BRCA1/2 mutations, carboplatin chemotherapy brought about more clinical benefits than standard docetaxel chemotherapy." (PMID 35494043, 2022). "The use of platinum-based agents provides patients with BRCA1/2 germline variants with triple negative breast cancer new avenues for future treatment regimens." (PMID 35685436, 2022). "It is well known that triple negative breast cancers and high grade serous ovarian cancers are typically characterized by BRCA1 mutations." (PMID 34031376, 2021). "Double heterozygous PALB2 c.758insT and BRCA1 c.927delA mutations have also been identified in a German patient with triple-negative breast cancer." (PMID 34439348, 2021). "The Ki67% proliferation index, the prevalence of triple negative breast cancer (TNBC) or multiplex HBOC were increased only when the c.9976A>T variant accompanied a pathogenic BRCA1 variant." (PMID 33672545, 2021). "Poly-(ADP)-ribose polymerase inhibitors (PARPi) and platinum-based drugs are promising therapies for triple negative breast cancers (TNBC) with BRCA1 or BRCA2 loss." (PMID 34367977, 2021). "By contrast, triple-negative breast cancer was more common among women with BRCA1 than BRCA2 mutations (28.38% vs. 7.46%)." (PMID 33649363, 2021). "The aim of this paper is to evaluate the probability of pCR in triple-negative breast cancers patients, treated mostly with the recommended, neoadjuvant schedule AC followed by taxane chemotherapy, based on BRCA1 gene mutation status." (PMID 34201809, 2021). "The chemotherapy regimen with adriamycine, cyclophosphamide, and taxans can be effectively used in triple-negative breast cancer patients, even with BRCA1 mutation." (PMID 34201809, 2021). "Olaparib is effective in metastatic triple negative breast cancer (TNBC) carrying germline mutations in DNA damage repair (DDR) genes BRCA1/2 (gBRCA-mut)." (PMID 34262869, 2021). "As already discussed, triple-negative breast cancer is strongly associated with germline mutations in the BRCA1 gene and can be much more sensitive to platinum agents." (PMID 34201809, 2021). "BRCA1 mutations frequently give rise to the aggressive, higher-grade, triple-negative breast cancer subtype." (PMID 35008272, 2021). "Of the 8 patients with a PV or LPV, only one had a previous history of cancer: a BRCA1 mutation carrier, diagnosed with PC at the age of 69, had two triple-negative breast cancers (TNBCs), at 42 and 55 years." (PMID 34034685, 2021). "The aim of this study was to evaluate the probability of pathologic complete regression (pCR) by the BRCA1 gene mutation status in patients with triple-negative breast cancer (TNBC) treated with neoadjuvant chemotherapy." (PMID 34201809, 2021). "Approximately 25% of patients diagnosed with triple negative breast cancer carry a germline BRCA1 or BRCA2 mutation." (PMID 34900718, 2021). "Basal-like cancers are usually triple-negative breast cancers, which harbor more germline mutations of BRCA1 and BRCA221,22." (PMID 34140574, 2021). "In this small neoadjuvant study among 32 triple negative breast cancer patients, somatic mutations in non-BRCA1/2 HR-related genes were found to be predictive for a response to olaparib (objective response rate 100% (5/5))." (PMID 33670893, 2021). "Recently, a new class of molecules has emerged as a standard of care for patients with triple negative breast cancer and germline BRCA1 or BRCA2 mutation: poly (ADP-ribose) (PARP) inhibitors." (PMID 34900718, 2021).
triple-negative breast carcinoma (continued). "In our cohort, we found an enrichment of triple-negative breast cancers in BRCA1 mutation carriers and hormone receptor-positive cancers in BRCA2 mutation carriers." (PMID 33649363, 2021). "Poly (ADP-ribose) polymerase (PARP) inhibitors offer a significant clinical benefit for triple-negative breast cancers (TNBCs) with BRCA1/2 mutation." (PMID 33637776, 2021). "In the present study, a quarter of triple-negative breast cancer patients harbored a germline pathogenic variant and two-thirds of those were BRCA1 carriers." (PMID 35155181, 2021). "The BLBC cell line HCC1937 has a homozygous BRCA1 5382C* mutation and the triple negative breast cancer (TNBC) cell line MDA-MB-436 has a BRCA1 homozygous deletion." (PMID 34465787, 2021). "Given that 10% of triple-negative breast cancers harbor BRCA1/2 mutations, our results support consideration of the PBD-containing EGFR-targeted ADC (ABBV-321) within this specific subset of EGFR-expressing TNBC." (PMID 33256808, 2020). "For patients carrying BRCA1 mutations, at least one‐third develop triple negative breast cancer (TNBC)." (PMID 31989039, 2020). "BRCA1 inactivation is a hallmark of familial breast cancer, often associated with aggressive triple negative breast cancers." (PMID 32290274, 2020). "In the present study, we found BRCA1 promoter hypermethylation and loss of protein expression in about 68.75% (16/30) of patients with early stage (less than 45 years) triple negative breast cancer." (PMID 32856871, 2020). "Here, the authors show that hypermethylated BRCA1 phenotypically copies mutated BRCA1 in triple negative breast cancers." (PMID 32719340, 2020). "Genetically engineered BRCA1-deficient mouse models offer a unique opportunity to study the pathogenesis and therapy of triple negative breast cancer." (PMID 32053991, 2020). "There is another amplicon that has been associated with the BRCA1 mutated triple negative breast cancer in the region 17q25.3, that was also observed in HER2+ and Luminal B subtype." (PMID 32850369, 2020). "In patients with triple-negative breast cancer, BRCA1/2 mutation patients had higher pCR rates than those with BRCA wild-type patients." (PMID 32131779, 2020). "The most frequent variant BRCA1 c.3257del was detected in four unrelated patients with ER-/PR- status, and two patients were undertaking triple-negative breast cancer." (PMID 32879886, 2020). "It was reported that pathogenic mutations in BRCA1 normally result in triple-negative breast cancers (TNBC), while BRCA2 mutations typically cause the development of ER + luminal subtypes exhibiting a slow proliferation and low level of aggression." (PMID 32300589, 2020). "In triple-negative breast cancer, several studies have shown that in the relationships between germline BRCA1/2 mutations, response rates, and prognoses." (PMID 32131779, 2020). "In the second study, whose objective was the molecular analysis of the BRCA genes in 190 patients with triple negative breast cancer diagnosed before the age of 50 years, the 9–12 of the BRCA1 accounted for 41% of mutations identified." (PMID 31545835, 2019). "In the patients younger than 40 years old with triple-negative breast carcinomas, BRCA1/2 mutation positivity was found in 37.5% of the patients." (PMID 30713775, 2019). "In the triple-negative breast carcinoma patients younger than 60 years old, the BRCA1/2 mutation prevalence was 24.2%." (PMID 30713775, 2019). "Overall, BRCA1 mutations were more prevalent in the triple-negative breast carcinoma cases, while BRCA2 mutations were more prevalent in the hormone-positive tumors." (PMID 30713775, 2019). "In the German and Austrian community, in triple-negative breast carcinoma patients, the BRCA1/2 mutation prevalence was 21%." (PMID 30713775, 2019). "Triple negative breast cancer is known to be a marker of hereditary breast cancer susceptibility syndromes, such as BRCA1 mutations." (PMID 30834239, 2019).
triple-negative breast carcinoma (continued). "In the Canadian population, in triple-negative breast carcinoma patients under 40 years of age, the BRCA1/2 mutation prevalence was 11%." (PMID 30713775, 2019). "We found a significant association between the 9–12 del BRCA1 carriers with triple negative breast cancer and high-grade papillary serous ovarian cancer." (PMID 31545835, 2019). "In the Greek population, in triple-negative breast carcinoma patients, BRCA1/2 mutations were found in 16% of the patients." (PMID 30713775, 2019). "We observed a significant difference in the proportion of triple-negative breast cancer phenotype among 88.9%, 72.5%, and 26.8% of BRCA1 L63X mutation, BRCA1 mutation, and BRCA2 mutation carriers, respectively (p < .001)." (PMID 31143373, 2019). "In women with triple-negative breast carcinomas in the Hispanic population, the BRCA1/2 mutation prevalence was 23%." (PMID 30713775, 2019). "Another subgroup in which BRCA1/2 mutations are frequently seen is women with triple-negative breast carcinomas." (PMID 30713775, 2019). "In the patients under 40 years old, the BRCA1/2 mutation positivity prevalence was 19.5%, and in the patients under 60 years old with triple-negative breast carcinomas, the BRCA1/2 mutation positivity prevalence was 24.2%." (PMID 30713775, 2019). "The prevalence of pathogenic germline BRCA1/2 mutations in the selected triple-negative breast cancer patients ranged from 9.2 to 34.4%." (PMID 29928469, 2018). "In selected triple negative breast cancer cases, 57% were found to have BRCA1 and 23% BRCA2 germ line mutations." (PMID 29453630, 2018). "Compared with other patients, BRCA1 mutation carriers were younger (P < .001) and more likely to have triple-negative breast cancer (P = .028)." (PMID 30130155, 2018). "In unselected triple negative breast cancers, around 19% mutations were reported in the BRCA1/2 genes including also scattered somatic mutations (15% in BRCA and 3.9% in BRCA2 genes)." (PMID 29453630, 2018). "BRCA mutations were identified in 136 (24%) of patients with triple-negative breast cancer, of whom 123 (90%) had a BRCA1 mutation." (PMID 29337092, 2018). "Considering patients with triple-negative breast cancer, BRCA1 mutation dominancy was seen in both Asian and Caucasian populations." (PMID 29861850, 2018). "The 6.25% frequency of BRCA1 frame shift mutations in our study is lower than reported frequencies in unselected triple negative breast cancers or in sporadic cases or in serous high-grade ovarian carcinomas without family history varying from 19 to 28%)." (PMID 29453630, 2018). "Among 359 patients with triple-negative breast cancer, 101 (28.3%) had mutations for BRCA1 and 18 (5.0%) for BRCA2." (PMID 30203341, 2018). "DNA damaging agents such as cisplatin are widely used in the treatment of highly aggressive, triple-negative breast cancer and BRCA1/2-mutated tumors." (PMID 28881649, 2017). "The combination of the PARP inhibitor olaparib and rapamycin synergistically inhibited cell proliferation in non-small cell lung cancer (NSCLC) cells, and even in triple negative breast cancer (TNBC) cells with BRCA1 mutations." (PMID 29152062, 2017). "It has been suggested that all women with triple negative breast cancer aged <50 years should be tested for BRCA1/2 mutations based on the overall detection rate being above 10%." (PMID 27796713, 2017). "BRCA1 mutation is also frequently observed in triple negative breast cancer patients and has significant implications for the therapeutic response to PARP inhibitors and platinum compounds." (PMID 29096610, 2017). "Luminal B subtype should be considered as a high-risk population of BRCA1/2 mutation, in addition to triple-negative breast cancer." (PMID 27257965, 2016). "Emerging evidence suggests that BRCA1 pathway contributes to the behavior of sporadic triple negative breast cancer (TNBC), but little is known about the mechanisms underlying this association." (PMID 26933805, 2016).
triple-negative breast carcinoma (continued). "Past work has demonstrated that nuclear Kaiso expression is enriched in basal-like/triple-negative breast cancers and in BRCA1 associated invasive breast cancer, and is inversely correlated with cytosolic p120." (PMID 26939613, 2016). "More than half of the patients with the BRCA1 mutation had triple-negative breast cancer, and they also shared common clinical and pathological features." (PMID 27413552, 2016). "Women who carry a germline mutation in BRCA1 gene typically develop triple negative breast cancers (TNBC) and high grade serous ovarian cancers (HGSOC)." (PMID 28164176, 2016). "PARP inhibitors have been studied most extensively in HSOC and triple-negative breast cancer, and have proven particularly effective against cancers associated with BRCA1 or BRCA2 mutations." (PMID 27613518, 2016). "There were also other studies reported that triple-negative breast cancer (TNBC) patients with germline or somatic BRCA1/2 mutations had a significantly lower risk of relapse." (PMID 27257965, 2016). "Of the nine triple-negative breast cancer diagnoses in the present study, four occurred in patient's carriers of BRCA1 mutations." (PMID 26997744, 2016). "Here, we investigated if diagnosis of triple-negative breast cancer (TNBC) independently increases risk of carrying a BRCA1/2 mutation in Pakistan." (PMID 27553291, 2016). "Especially the aggressive entity of early stage triple negative breast cancer with BRCA1 promoter methylation is associated with a poor outcome." (PMID 27027444, 2016). "Mutations in BRCA1 were most frequent in patients with triple-negative breast cancer (18.4%), and mutations in CHEK2 were most frequent in patients with hereditary non-triple-negative breast cancers (15.9%)." (PMID 26083025, 2015). "Familial triple-negative breast cancers are often linked to mutations in the BRCA1 tumor suppressor gene." (PMID 26392359, 2015). "Triple negative tumors in BRCA1/2 mutated carriers showed a higher ANXA1 expression than triple negative breast cancer patients in the BCAC cohort (84.2 % versus 41.9 %, respectively; P <0.0001)." (PMID 26137966, 2015). "BRCA1 seems to be associated with the triple negative breast cancer (TNBC) subtype because the histological features and clinical outcomes of TNBC sporadic tumors can be very similar to those found in the tumors of BRCA1 germline mutated patients." (PMID 26490435, 2015). "The frequency of triple-negative breast cancer was 71.4% (5/7) in BRCA1 mutation carriers and 9.1% (1/11) in BRCA2 mutation carriers." (PMID 25927356, 2015). "Two patients diagnosed with triple negative breast cancer (TNBC) were screened for BRCA1 germline mutation." (PMID 25880076, 2015). "The BRCA1 tumor suppressor participates in DNA repair and is often mutated in triple-negative breast cancers." (PMID 25885960, 2015). "Ovarian and triple-negative breast cancers with BRCA1 or BRCA2 loss are highly sensitive to treatment with PARP inhibitors and platinum-based cytotoxic agents and show an accumulation of genomic scars in the form of gross DNA copy number aberrations." (PMID 26015868, 2015). "It is also noteworthy that one out of the five affected female cases had a triple negative breast cancer which is associated with pathogenic BRCA1 mutations." (PMID 24695549, 2014). "It is well established that families carrying a germline BRCA1 mutation have increased incidence of basal-like/triple-negative breast cancers, while germline BRCA2 mutations predispose to cancers of the lumB subtype." (PMID 24479546, 2014). "Of the remaining 61 patients with unselected triple-negative breast cancer, the BRCA1/2 mutation prevalence was 24.6% (15/61), and all 15 individuals with these mutations were premenopausal patients." (PMID 24961674, 2014).
triple-negative breast carcinoma (continued). "To confirm our in vitro findings, we evaluated BRCA1 protein expression using our CT cohort of triple negative breast cancer patient tumor samples, where BRCA1 protein staining and the BRCA1-3’UTR-variant genotype analysis was available." (PMID 24915755, 2014). "In some cancers, e.g. triple-negative breast cancer, DNA instability is an integral part of the process of tumorigenesis, and is driven by defects in DNA repair systems (e.g. mutations in BRCA1 or BRCA2), which result in further cancer-driving mutations." (PMID 25252808, 2014). "The direct relationship between BRCA1 mutations and triple negative breast cancer has been widely assessed in Greek patients." (PMID 24660075, 2014). "In support, the recent study from the Hellenic Cooperative Oncology Group found that only 27% of women with triple-negative breast cancer, unselected for family history, had a BRCA1 mutation." (PMID 23704984, 2013). "Variants at the BABAM1 locus, encoding a BRCA1 binding partner also known as MERIT40, have been specifically associated with triple-negative breast cancer and serous epithelial ovarian cancer, which resembles the picture seen with BRCA1 mutations." (PMID 24025454, 2013). "A recent study reported a 16% prevalence rate of germline BRCA1 mutations among unselected triple-negative breast cancers." (PMID 23704984, 2013). "More than half of patients with BRCA1 mutation have triple-negative breast cancer, and share common clinical and pathological features." (PMID 23405268, 2013). "A statistically significant association was found between BRCA1 promoter methylation and triple-negative breast cancer (ER-/PR-/HER2-) in this cohort of patients (p = 0.041)." (PMID 23405268, 2013). "Recently, BRCA1 germline mutations were found in a high proportion (14–34%) of patients with triple-negative breast cancer (TNBC)." (PMID 22666503, 2012). "Triple-negative breast cancers frequently carry mutations of the BRCA1 gene, for this reason, they turn out to be sensitive to platinum compounds." (PMID 22290080, 2012). "In particular, PARP inhibitors were applied, taking advantage of a disturbed DNA-repair due to frequent BRCA1-mutations present in triple-negative breast cancer." (PMID 22290080, 2012). "Both cisplatin and gemcitabine should be explored in clinical trials for first line regimens for BRCA1-associated and triple-negative breast cancer." (PMID 21771338, 2011). "With the exception of PARP inhibitors, an investigational therapeutic strategy for BRCA-deficient cancers, empirically chosen cytotoxic chemotherapy is the primary option for treating patients with BRCA1-associated and triple-negative breast cancer." (PMID 21771338, 2011). "Collectively, these results indicate that curcumin induces DNA damage in triple negative breast cancer cells, which is associated with phosphorylation and expression of the BRCA1 DNA repair protein." (PMID 19809577, 2009). "The current study demonstrates that curcumin induces DNA damage and apoptosis in triple negative breast cancer cells in association with increased expression, phosphorylation, and cytoplasmic retention of the BRCA1 protein." (PMID 19809577, 2009). "We demonstrate here that the bioactive food compound curcumin induces DNA damage in triple negative breast cancer cells in association with phosphorylation, increased expression, and cytoplasmic retention of the BRCA1 protein." (PMID 19809577, 2009). "Moreover, PARP3 inhibition shows selective lethality in BRCA1-deficient triple-negative breast cancer (TNBC) cells compared to BRCA1-proficient cells." (PMID 40741921, 2025). "However, in one of our study patients, with triple-negative breast cancer and a family history, the BRCA1 variant (c.5099C>T, p.Thr1700Ile) had changed from a VUS at the time of testing to likely pathogenic in the latest ClinVar database." (PMID 39831988, 2025).